GLP1R (glucagon like peptide 1 receptor)
Diseases named in the same sentence as GLP1R in open-access papers (continued):
Sharing a sentence is not in itself a finding about the gene and the disease.
Obesity (continued). "Glucagon-like peptide-1 receptor agonists (GLP-1RAs) have transformed the therapeutic landscape of type 2 diabetes (T2D) and obesity by offering substantial weight loss and cardiometabolic protection." (PMID 41201615, 2025). "Further studies specifically evaluating BAT activity in individuals living with obesity treated with GLP-1R agonist-based therapies are needed to draw firm conclusions on BAT activation in patients." (PMID 40892365, 2025). "Novel glucagon-like peptide-1 receptor agonists (GLP1RAs) for obesity treatment have generated considerable dialogue on digital media platforms." (PMID 41284989, 2025). "The role of GLP-1 agonists with a strategy of its receptor (GLP-1R) activation or sustained levels of increased GLP-1 has been established as a potential therapeutic strategy for weight management and obesity-associated type-2 diabetes." (PMID 40655199, 2025). "Given the overlap of MASLD with obesity and diabetes, GLP-1R agonists have been recognized as potential treatment options for MASH." (PMID 40494889, 2025). "Limited access to specialist weight management services restricts the implementation of novel pharmacotherapies for obesity such as glucagon-like peptide-1 receptor agonists (GLP-1RAs) in the UK National Health Service (NHS)." (PMID 40434299, 2025). "GLP-1R agonists first received approval by the US Food and Drug Administration in 2005 (exenatide) and for treatment of obesity in 2015 (liraglutide)." (PMID 40892365, 2025). "Unlike most other older medications for the treatment of type 2 diabetes mellitus, glucagon-like peptide-1 receptor agonists (GLP-1 RAs) promote weight loss addressing the common type 2 diabetes comorbidity, obesity." (PMID 40981248, 2025). "As apparent from the parallel development of drugs combining GLP1R agonism with either GIPR agonists or antagonists for the treatment of obesity, GIP appears to have several, sometimes opposing, actions on the brain." (PMID 40166681, 2025). "Recent advancements in obesity pharmacotherapy have seen the approval of novel agents, like glucagon-like peptide-1 receptor agonist and dual agonists, offering unprecedented efficacy for obesity management." (PMID 40607226, 2025). "Glucagon-like peptide 1 (GLP-1) receptor (GLP-1R) agonism is foundational to modern obesity pharmacotherapies." (PMID 40157531, 2025). "The co-activation of these two receptors enhances β cell function, offering a more effective treatment for diabetes and obesity with a reduced adverse effect profile compared to selective GLP-1R agonists." (PMID 40566497, 2025). "Recent years have seen remarkable advancements in obesity treatment achieved by the development of new drugs that combine GLP-1R and GIPR co-agonism in a single molecule." (PMID 40892365, 2025). "Conversely, anti-obesity medications based on glucagon-like peptide-1 receptor agonists appear to have a protective effect against the development of MS." (PMID 39885338, 2025). "Improvements have been made in monotherapies to treat obesity, particularly within the family of drugs that target the glucagon-like peptide-1 receptor (GLP-1R)." (PMID 39502365, 2025). "In the mesolimbic system, GLP-1R activation has been shown to attenuate the rewarding effects of palatable food and addictive substances, indicating potential therapeutic applications for GLP-1R agonists in treating obesity and SUDs." (PMID 40508146, 2025). "Over the past decade, significant advancements have been made in the development of anti-obesity therapies, particularly with the emergence of the incretin-mimetic therapies, such as glucagon-like peptide-1 receptor agonists (GLP-1 RAs)." (PMID 41400711, 2025). "We evaluated whether concurrent glucagon-like peptide-1 receptor agonist (GLP-1 RA) plus sodium-glucose cotransporter 2 inhibitor (SGLT2i) use before solid-organ transplantation was associated with post-transplant outcomes in adults with obesity and type 2 diabetes." (PMID 41387113, 2025).
Obesity (continued). "Currently, selective GLP-1R agonists have been approved for clinical use in the management of T2D and obesity, owing to their potent glycemic and weight-regulatory effects." (PMID 40243679, 2025). "Glucagon-like peptide-1 receptor agonists (GLP-1 RAs) (such as liraglutide or semaglutide) have gained prominence as obesity treatments." (PMID 40718355, 2025). "In the SUMMIT trial, patients with HFpEF and obesity were randomized to the long-acting glucose-dependent insulinotropic polypeptide receptor and glucagon-like peptide-1 receptor agonist tirzepatide (n = 364, 200 women) or placebo (n = 367, 193 women)." (PMID 39551891, 2025). "A large-scale epidemiological studycompared the incidence of obesity-related cancers in patients treated with GLP1R agonists versus those treated with insulin or metformin." (PMID 39777709, 2025). "Obesity remains a major global health challenge, with glucagon-like peptide-1 receptor agonists (GLP-1RAs) providing substantial yet sensitive benefits in weight reduction, glycemic control, and cardiovascular protection." (PMID 41463089, 2025). "What is the projected 10-year fiscal impact on the Medicare program if Part D plans were to cover glucagon-like peptide-1 receptor agonists (GLP-1RAs) for obesity treatment?" (PMID 40279111, 2025). "This cohort study describe rates of and factors associated with discontinuation and subsequent reinitiation of glucagon-like peptide-1 receptor agonists among more than 125 000 adults with overweight or obesity." (PMID 39888616, 2025). "A new era in the treatment of obesity has emerged with the development of glucagon-like peptide-1 receptor agonists (GLP-1 RAs)." (PMID 41515247, 2025). "A novel direction in the management of obesity and diabetes has emerged through the utilization of GLP-1R agonists, which stimulate insulin release in a glucose-dependent manner." (PMID 39692365, 2025). "One potential intriguing avenue of investigation lies in the use of glucagon‐like peptide‐1 receptor (GLP‐1R) agonists, which have been primarily prescribed for the treatment of type II diabetes and obesity." (PMID 40525593, 2025). "This case underscores the potential of glucagon-like peptide 1 receptor agonists (GLP-1 RAs) in managing both obesity and behavioral symptoms in SMS." (PMID 40443456, 2025). "The main mechanism of the therapeutic effect of GLP-1R agonists in obesity is considered to be via reduced calorie intake, and this is also considered to be true for their therapeutic effects on MASH2." (PMID 40968135, 2025). "Several studies have investigated the benefits of GLP-1R agonists and GLP-1R-GIPR co-agonists, both used for combating obesity, which is an increased risk factor or directly affects the course of various pathologies." (PMID 41464694, 2025). "We also discuss the implications of this for the development of GLP-1R poly-ligands, which are increasingly pursued for the treatment of obesity and other diseases." (PMID 40806371, 2025). "The glucagon-like peptide 1 receptor (GLP-1R) agonist semaglutide has revolutionized the treatment of obesity, with other gut hormone-based drugs lined up that show even greater weight-lowering ability in obese patients." (PMID 39644359, 2025). "Glucagon-like peptide-1 receptor agonists (GLP-1 RAs) are increasingly prescribed among plastic surgery patients for obesity and overweight." (PMID 41445996, 2025). "With the recent approvals of semaglutide and liraglutide for the treatment of obesity, the GLP-1R agonists have once again gained attention within the research and clinical communities." (PMID 41471111, 2025). "Despite nine AOMs being currently approved for the treatment of obesity, limited clinical trial evidence in older adults predominantly focuses on incretin therapy with glucagon-like peptide-1 receptor agonists (liraglutide, semaglutide, and tirzepatide)." (PMID 38710803, 2025).
Obesity (continued). "Among pharmacological options, glucagon-like peptide-1 receptor (GLP-1R) agonists have emerged as a breakthrough in the treatment of obesity." (PMID 40732345, 2025). "Modern obesity therapy is reliant on drugs that activate the GLP-1R, including semaglutide and tirzepatide." (PMID 40157531, 2025). "The development of the GLP1R/GIPR dual agonist tirzepatide brought new insights into the role of GIP in the treatment of T2D and obesity because it can reduce both plasma glucose and glycated haemoglobin more effectively than the GLP1R agonist semaglutide." (PMID 39576749, 2025). "Recently, a superior efficacy of dual GLP-1R/GCGR agonism versus single GLP-1 agonism in reducing obesity in mice has been attributed to a remodelling of WAT towards browning and UCP-1-dependent BAT activation." (PMID 40892365, 2025). "The development of treatment strategies that target both the GIPR and the GLP-1R system represents a significant breakthrough in the fight against obesity and T2DM." (PMID 40532005, 2025). "Collectively, these observations strengthened the reliability of GLP-1R agonist-based drug therapies for obesity." (PMID 39974186, 2025). "OXM will probably redefine the landscape of obesity and metabolic therapies, providing an unparalleled physiological approach by simultaneously targeting GLP1R and GCGR." (PMID 39495024, 2025). "The most recently approved FDA medication for the treatment of obesity, tirzepatide, exerts its physiologic effects as a dual GLP-1R and Gastric Inhibitory Polypeptide Receptor (GIP-R) agonist with better efficacy than the standalone GIP-R agonist semaglutide." (PMID 40722684, 2025). "Incretin receptor agonists including GLP-1R agonists and dual GLP-1R/GIPR co-agonists reduce food intake and drive weight loss in patients with obesity." (PMID 39963285, 2025). "Among the most promising candidates for MASLD-related treatment are glucagon-like peptide-1 receptor agonists (GLP-1 RAs), given their proven efficacy in the management of obesity and T2DM–key pathogenic drivers of MASLD." (PMID 40863129, 2025). "Most recently, pharmaceutical companies have developed anti‐diabetic treatment through anti‐obesity approaches like GLP‐1R agonists or co‐agonists for glucose‐dependent insulinotropic polypeptide receptor (GIPR) and GLP‐1R." (PMID 41208560, 2025). "There has been great interest in targeting the glucose-dependent insulinotropic polypeptide receptor (GIPR) as a means of augmenting the insulinotropic and anti-obesity action of glucagon-like peptide-1 receptor (GLP-1R) agonists." (PMID 39788289, 2025). "The satiety phase eventually terminates a meal as well as the tendency to initiate feeding due to peripheral signals that can be recapitulated by anti-obesity drugs, such as GLP-1R agonists." (PMID 40146831, 2025). "These preclinical findings support clinical trial results showing that tirzepatide, a dual GIPR/GLP-1R agonist, exhibits greater anti-obesity effects than GLP-1 receptor agonists alone." (PMID 40607142, 2025). "More recent studies have extended the cardiovascular benefits of GLP-1R agonism to people with obesity, and subjects with heart failure and preserved ejection fraction (HFpEF)." (PMID 38226625, 2024). "Weight-loss injections, such as glucagon-like peptide-1 receptor (GLP-1) agonists, have gained popularity for their effectiveness in reducing obesity-related comorbidities." (PMID 39483584, 2024). "Approved for obesity treatment, Liraglutide, a GLP-1R agonist, has shown promise in enhancing objective measures of cognitive function in adults diagnosed with mood disorders." (PMID 38637833, 2024). "Due to its potent effects on glucose homeostasis and appetite regulation, GLP-1R agonists are treatments for type 2 diabetes and obesity." (PMID 38997662, 2024). "In contrast, Gipr–/– mice exhibit greater resistance to diet-induced obesity, relative to Glp1r–/– mice." (PMID 38226625, 2024).
Obesity (continued). "Recently, the market for anti-obesity treatments has grown drastically due to the release of glucagon-like peptide 1 receptor (GLP-1R) agonists, which can help reduce body weight and showcases antidiabetic effects." (PMID 39065646, 2024). "This review examines the impact of obesity on the pathophysiology of heart failure with preserved ejection fraction (HFpEF) and focuses on novel mechanisms for HFpEF prevention using a glucagon-like peptide-1 receptor agonism (GLP-1 RA)." (PMID 38673991, 2024). "Bariatric metabolic surgery (BMS) and glucagon-like peptide-1 receptor agonists (GLP-1RAs) represent two prominent therapeutic approaches for obesity and its cardiovascular complications." (PMID 39552962, 2024). "Given the association between obesity, IR, and PCOS, GLP-1R agonists were considered in the treatment of PCOS, and studies have shown that GLP-1R agonists do have therapeutic effects on PCOS." (PMID 39858999, 2024). "Metabolic surgery and GLP-1R drugs provided great options for patients with obesity and metabolic syndrome." (PMID 39807334, 2024). "Approved therapies for obesity and overweight include phentermine/topiramate, orlistat, naltrexone/bupropion, the glucagon-like peptide-1 receptor agonists liraglutide and semaglutide, tirzepatide, and bariatric surgery." (PMID 39457606, 2024). "GLP-1R agonists have effectively managed obesity by reducing hunger, moderating food intake, and regulating body weight." (PMID 38801466, 2024). "Here, we briefly summarized the beneficial effects of GLP-1R agonists other than the anti-diabetic and anti-obesity effects." (PMID 39858999, 2024). "Exercise prevented obesity and improved metabolic state in SL overnourished rats, and normalized their hypothalamic Lep-R and GLP1-R gene expressions." (PMID 39258689, 2024). "For children with concurrent obesity, there is emerging evidence to support a potential role for glucagon-like peptide-1 receptor (GLP-1R) agonists." (PMID 38806767, 2024). "Previous studies showed that GLP1R agonists are effective in improving obesity-related hepatic dysfunction but presumably through indirect effects." (PMID 39266553, 2024). "Hyperglycemia has previously been reported to induce GLP-1R downregulation in pancreatic islets, and vascular GLP-1R is reduced in humans with obesity." (PMID 39582036, 2024). "It is also possible that β-cells under obesity and T2D display GLP-1R’s signaling shift to Gq, due in part to insufficient XBP1s’ and ATF6′s action enhancing GLP-1R’s Gs use." (PMID 38376482, 2024). "Emerging data suggest a potential role of GLP-1R agonists in treating a multitude of conditions beyond obesity and T2D, ranging from hypertension to dementia." (PMID 39931650, 2024). "This has contributed to the characterization of the mechanisms by which glucagon-like peptide-1 receptor agonists promote body mass reduction and has opened new windows of opportunity for the development of drugs to treat obesity." (PMID 39876968, 2024). "As the emerging anti-diabetic and anti-obesity drugs, GLP-1R agonists are widely used in clinical practice with the effects of reducing blood glucose and body weight." (PMID 39858999, 2024). "The impact of BMI on cancer-risk reduction in our study reveals a complex relationship between obesity severity and GLP-1R agonists’ cancer-protective effects." (PMID 39796706, 2024). "More recently developed monotherapies to treat obesity such as the long-acting glucagon-like peptide-1 receptor (GLP-1R) agonists, liraglutide and semaglutide, produce more pronounced effects on weight loss relative to previous analogues." (PMID 39104812, 2024). "This meta-analysis provides compelling evidence that bariatric metabolic surgery (BMS) offers superior cardiovascular protection compared to glucagon-like peptide-1 receptor agonists (GLP-1RAs) in patients with obesity." (PMID 39552962, 2024).
Obesity (continued). "The maturation of incretin biology has led to the development of anti-obesity drugs that potently activate GLP-1R and/or GIP receptors (GIPR), setting new and even higher standards for performance." (PMID 36834794, 2023). "The therapeutic spectrum of T2D and obesity therapy has recently been enriched by hybrid peptides acting as triple GLP-1R/GIPR/GCGR agonists that target both incretin and glucagon signalling to synergistically elicit favourable metabolic effects." (PMID 37378828, 2023). "The advent of novel, second-generation anti-obesity medications, from currently approved glucagon-like peptide 1 receptor agonists (GLP-1RAs) to new agents in the pipeline, now provide powerful tools for the management of adiposity-based chronic diseases." (PMID 37239935, 2023). "In recent years, several anti-obesity agents have become available, such as glucagon-like peptide-1 receptor agonists (GLP-1 RA, i.e. liraglutide or semaglutide), and naltrexone-bupropion (NB)." (PMID 36876127, 2023). "Many clinical trials have proven GLP-1R agonists’ effectiveness and safety in treating or preventing obesity." (PMID 36843578, 2023). "In comparison to mono-agonist therapies, the GLP-1R/GIPR co-agonist significantly reduced obesity, glucose intolerance, non-alcoholic fatty liver disease, and dyslipidemia in both the male and female mice." (PMID 37375734, 2023). "Researchers interested in this direction can see more details on the efficacy of GLP-1R/GCGR agonists in the treatment of obesity in Sanchez-Garrido’s review." (PMID 36843578, 2023). "The recent introduction and widespread use of glucagon-like peptide 1 receptor (GLP-1R) agonists presents new opportunities to study the therapeutic potential of these anti-obesity medications on nicotine dependence in individuals displaying T2D." (PMID 38389818, 2023). "Two independent papers reported for the first time the use of GLP1R/GCGR dual agonists as being of enhanced efficacy relative to pure GLP1R agonists in the treatment of rodent obesity, with simultaneous improvement in glycemic control." (PMID 38161982, 2023). "GLP-1 analogs, also known as GLP-1R agonists, have become popular anti-diabetic drugs in recent years because of their additional anti-obesity effect." (PMID 37435495, 2023). "GLP1R agonism has confirmed benefits in obesity, but the mechanisms behind these changes are still being studied." (PMID 38201269, 2023). "Glucagon-like peptide-1 receptor agonists (GLP-1 RA) are promising agents in the treatment of obesity with potential applications to MFI." (PMID 38256311, 2023). "Semaglutide is the first long-acting and orally-administered GLP-1R agonist that has been clinically approved for the treatment of type II diabetes and obesity." (PMID 37295046, 2023). "We anticipate that this review will generate data that will help biomedical researchers or clinical workers develop obesity treatments based on GLP-1R agonists." (PMID 36843578, 2023). "Together, these data highlight the need to consider the individual food environment and personal history in the success of anti-obesity interventions for GLP1R agonists." (PMID 37293487, 2023). "Two GLP-1R agonists have been approved in the United States to treat obesity: semaglutide and LIR, both of which are injected subcutaneously." (PMID 36843578, 2023). "In an obesity cohort (BMI≥35), the post-surgery usage of Ex-9 (a specific GLP-1R antagonist) completely reversed improvements in β-cell glucose sensitivity and glucose tolerance, implicating the critical role of activated GLP-1 response in this process." (PMID 36875493, 2023). "As insulin resistance and obesity are strong risk factors for nonalcoholic fatty liver disease (NAFLD), in the current study we investigated the effects of combined GIPR/GLP1R agonism on NAFLD development." (PMID 37379656, 2023).